RN7SL803P (RNA, 7SL, cytoplasmic 803, pseudogene)
Gene: Miscellaneous RNA gene on chromosome 5 (154,718,383 to 154,718,689, reverse strand). Ensembl gene ENSG00000272197.
Homologues: Orthologues: chimpanzee Metazoa_SRP (99% identical), macaque Metazoa_SRP (96% identical), rabbit Metazoa_SRP (64% identical). Paralogues in human: RN7SL1 (82% identical), RN7SL2 (81% identical), RN7SL45P (80% identical), RN7SL3 (80% identical), RN7SL680P (79% identical), RN7SL712P (79% identical), RN7SL769P (79% identical), RN7SL7P (79% identical), RN7SL652P (79% identical), RN7SL91P (79% identical), RN7SL230P (79% identical), RN7SL322P (79% identical), and 705 more.